GPX4 (glutathione peroxidase 4)
Diseases named in the same sentence as GPX4 in open-access papers (continued):
Sharing a sentence is not in itself a finding about the gene and the disease.
tumor (continued). "Administration of dihydroorotate or orotate, the substrate or product of DHODH, respectively, can attenuate or potentiate the ferroptosis induced by GPX4 inhibition, especially evident in tumor cells expressing low levels of GPX4." (PMID 39614322, 2024). "Researchers have explored the antitumor molecular mechanism of ML210 to inhibit GPX4 and reported a tumor-suppressive effect in a variety of tumors." (PMID 38200609, 2024). "GPX4 and xCT are the most critical proteins for avoiding ferroptosis, thus, their inhibition can lead to ferroptosis in tumor cells and enhance cell death after conventional medical treatment." (PMID 38469234, 2024). "Studies have reported that Epstein–Barr virus (EBV) infection-induced GPX4 can enhance chemoresistance and promote tumour progression by inhibiting ferroptosis." (PMID 38228715, 2024). "Surrounding this central node are significant terms like “apoptosis,” “immunotherapy,” “tumor microenvironment,” “ROS,” and “GPX4,” highlighting these as foundational and recurrent topics in the field." (PMID 38312575, 2024). "In tumor tissues, increased oxidative stress and enhanced nutritional metabolic demands lead to abnormal expression of GPX4 and xCT in various tumor cells, contributing to drug resistance." (PMID 39430236, 2024). "The western blot and IHC staining of xenografts tumor tissues showed that the protein levels of NRF2 and GPX4 of xenograft tumor tissues were significantly reduced by PEG-Fe3O4@C5aRA exposure." (PMID 39483473, 2024). "This interaction prevents the heat shock protein 70 from binding to GPX4, thereby inhibiting the degradation of GPX4 via chaperone-mediated autophagy, which in turn inhibits ferroptosis and supports tumor growth in mice." (PMID 39595619, 2024). "The induction of ferroptosis through GPx4 inhibition has emerged as a novel strategy to promote tumor cell death and enhance immune system activation." (PMID 39594547, 2024). "The COAD dataset retrieved from the TCGA database was analyzed, and the expression data of "GPX4" and "FoxO3" in tumor patients were extracted." (PMID 39668836, 2024). "Here the authors report a peptide ferriporphyrin conjugate to improve tumour penetration, endocytosis and GPX4 inhibition, synergistically enhancing its anticancer activity by ferroptosis." (PMID 38212623, 2024). "By promoting the Fenton reaction, inhibiting the Xc‐system/GPX4 and regulating the level of lipid peroxidation in tumour cells, these can effectively activate and amplify the iron death effect and kill tumours." (PMID 39163517, 2024). "Inhibition of GPX4 expression in breast cells can trigger ferroptosis, a form of iron-dependent cell death, which can suppress tumor cell proliferation and induce cell apoptosis." (PMID 38244591, 2024). "After that, this process was repeated in melanoma-related CD8+ T cells with the help of a high-throughput in vitro pharmacologic screening platform, and overexpression of GPX4 can effectively restore the anti-tumor immune effect of T cells." (PMID 38475936, 2024). "When tumor cells endocytosed NPs, progressively released RSL3 blocked GPX4 and Fc caused LPO by inducing ·OH generation through Fenton-like processes." (PMID 39276361, 2024). "We further detected the expression of ferroptosis‐associated proteins (HMGCR, GPX4) and pyroptosis‐associated proteins (such as NLRP3, GSDMD) in tumor tissues by using immunohistochemistry or western blot." (PMID 38178583, 2024). "Collectively, these data strongly demonstrated that LASS2 requires TFRC as a direct target to induce GPX4-dependent ferroptosis and thus inhibit tumour metastasis." (PMID 38419028, 2024). "For instance, in cases of hepatocellular carcinoma, the reduction of GPX4 proves ineffective in inhibiting cancer cell proliferation and instead leads to the impairment of anti-tumor immune cell functionality." (PMID 38853203, 2024).
tumor (continued). "GSH has been shown to act as a reductive co-substrate for GPX4, inducing GPX4 inactivation and thereby triggering ferroptosis in tumour cells." (PMID 38911386, 2024). "Typically, ferroptosis inducers have limited effectiveness against tumor types with high GPX4 expression." (PMID 39065721, 2024). "GPX4 is a central modulator of ferroptosis, and direct targeting of GPX4 to induce ferroptosis in tumour cells is a prospective strategy for the exploitation of therapeutic anticancer drugs." (PMID 39163517, 2024). "The depletion of GSH and decreased activity of glutathione peroxidase GPX4 can lead to lipid peroxidation and metabolic dysfunction, increasing the sensitivity of tumor cells to ferroptosis." (PMID 38200525, 2024). "The expression of antiferroptosis marker GPX4 in tumor issue demonstrated a decreasing tendency by western blot and immunochemistry staining, confirming the in vivo occurrence of ferroptosis." (PMID 38774917, 2024). "The MnFe2O4 in the MGNH nanoparticles reacted with endogenous H2O2 to promote lipid peroxidation in tumor cells and hampered GPX4 expression to induce ferroptosis." (PMID 39335181, 2024). "Several studies have shown that suppressing system xc- or GPX4 inhibits tumor growth and metastasis in various types of cancer." (PMID 38738174, 2024). "In the LAR subtype of TNBC, elevated GPX4 levels enhance anti-tumor immunity; however, inhibiting GPX4 induces ferroptosis, particularly when combined with anti-PD1 therapy, leading to greater efficacy compared to monotherapy." (PMID 39867656, 2024). "In view of the relationship between GPX4 and macrophages and immune B cells, a lot of studies are analyzing GPX4's role in tumor immunotherapy." (PMID 38333875, 2024). "It has been shown that circDTL is upregulated in NSCLC tissues and cell lines, and circDTL knockdown increases the apoptosis, ferroptosis, chemosensitivity, and in vivo tumor growth of NSCLC via the circDTL/miR-1287-5p/GPX4 axis." (PMID 38778030, 2024). "It was also discovered that the contents of OPN, p-PI3K, p-Akt, mTOR as well as GPX4 in tumor tissues of mice in the OPN-OE group were rapidly elevated in comparison with the Vector group." (PMID 38526702, 2024). "Together, these results indicated that the depletion of PSMD14 inhibited BC tumor growth in vitro and in vivo by targeting GPX4." (PMID 36632137, 2023). "Western blotting and immunohistochemical staining confirmed that GPX4 expression was downregulated in the tumor lesions formed by NeuroD1-knocked down HCC-LM3 cells." (PMID 38134213, 2023). "In summary, our study revealed a novel function of NeuroD1 in the transcriptional regulation of GPX4 and demonstrated its critical role in tumor cell ferroptosis resistance through direct binding to GPX4 promoter and activation of its transcriptional activity." (PMID 38134213, 2023). "The mouse xenograft model revealed that GPX4 knockdown inhibited tumor cell growth and prolonged the survival time of mice." (PMID 37649598, 2023). "Compared to that in peritumor tissues (n = 160), the expression of GPX4 gene was significantly increased in tumor tissues (n = 369) of HCC patients." (PMID 37554285, 2023). "Inhibition of GPX4 is reported to induce ferroptosis in persister tumor cells, the source of drug-resistant tumor cells." (PMID 36576648, 2023). "The expression of GPX4 was correlated with tumor location (P = 0.020), mitotic index (P = 0.019) and NIH risk grade (P = 0.005)." (PMID 38110356, 2023). "Ferroptosis is a metabolic vulnerability of tumor-specific CD8+ T cells, whereas GPX4-deficient T cells display a high sensitivity to ferroptosis and are thus incapable of exerting antitumor effects." (PMID 36937406, 2023). "Targeted inhibition of LCN2 by anti-LCN2 monoclonal antibody (3D12B2) increases intracellular iron levels, decreases GPX4 expression, and induces ferroptosis in tumor cells, thereby overcoming resistance." (PMID 38273826, 2023).
tumor (continued). "At the protein level, APS increased the phosphorylation of AMPK and BECN1 in tumor tissues, and APS decreased the protein expression of GPX4 in tumor tissues." (PMID 37733667, 2023). "The same tendency was also confirmed by tumor morphology, which showed significantly smaller tumors formed by NeuroD1-knocked down HCC-LM3 cells and a clear restoration effect by overexpression of GPX4, as well as by tumor weight." (PMID 38134213, 2023). "KRAS-mutant LUAD cells express high levels of SLC7A11 and GPX4; pharmacological or genetic inhibition of either SLC7A11 and GPX4 attenuates tumor growth in vivo." (PMID 37161053, 2023). "IHC staining confirmed the promotive effects of FOXA2 on GPX4 and Nrf2, as indicated by the obviously enhanced positive expression of GPX4 and Nrf2 in tumor samples collected from oe‐FOXA2 mice." (PMID 37875418, 2023). "The results showed that the expression of PRMT9, HSPA8, and GPX4 were significantly higher in tumor than that in adjacent tissues." (PMID 37715221, 2023). "Based on different mechanisms of action, ferroptosis inducers can be roughly divided into iron metabolism inducers, system xc–inhibitors, and GPX4 inhibitors, which are mostly used in the treatment of tumours and neurological diseases." (PMID 37954843, 2023). "Recent studies have indicated that GPX4 plays an essential role in tumor resistance to chemotherapy or radiotherapy." (PMID 37248295, 2023). "Another substance, Rhamnazin, can inhibit tumor proliferation and invasion by suppressing GPX4 expression and further upregulating the level of lipid peroxides, iron and ROS." (PMID 37124203, 2023). "More importantly, tumor metastases to the liver and lungs were most prevalent in 10–12-month Pdx1-Cre, KrasG12D/+, Gpx4−/− mice." (PMID 37488128, 2023). "As an efficient inhibitor of ferroptosis, GPX4 has provided drug resistance to tumor therapies, which is a significant challenge in the clinic with novel molecular targets and therapeutic strategies." (PMID 36675129, 2023). "We recently showed that FSP1 represents a powerful backup system for the guardian of ferroptosis, known as GPX4, rendering tumours resistant to inhibition of this node." (PMID 37380771, 2023). "Based on GSEA and CIBERSORT analysis, tumor cells with low GPX4 tend to be infiltrated by higher proportion of CD4+ T cell, expression of NOX1 was negatively correlated with M1 macrophage infiltration and ACSL4 was positively close to CD8+ T cell infiltration." (PMID 35855531, 2023). "Previously, it was found that inhibition of GPX4 activity and expression activated ferroptosis and effectively inhibited tumor progression." (PMID 36744249, 2023). "Meanwhile, the expression level of SLC7A11 and GPX4 was correlated with tumour diameter and distant metastasis (P<0.05)." (PMID 37807410, 2023). "Studies have shown that CD8+ T cells exhibit greater sensitivity to GPX4 inhibitors than tumor cells and ACSL4 gene deletion protects CD8+ T cells from ferroptosis." (PMID 36861444, 2023). "Ferroptosis inducers have demonstrated efficacy in tumour cells by directly binding to and inhibiting GPX4." (PMID 38273826, 2023). "SLC7A11 protein was positively expressed in 78 tumour tissues, but only 37 in normal tissues; meanwhile, GPX4 protein was positively expressed in 72 tumour tissues, while only 33 cases exhibited positive staining in normal tissues." (PMID 37807410, 2023). "In such extensive studies, statins—which inhibit GPx4 biosynthesis—were shown to decrease tumor cell resistance to cytotoxic antitumor drugs by synergizing with GPx4 inhibitors such as RSL3." (PMID 37373256, 2023). "For instance, the ferroptosis inducer erastin notably enhances cisplatin’s efficacy across various tumour types by antagonizing system Xc- or GPX4 functions." (PMID 38273826, 2023).
tumor (continued). "Tumour cells can bypass ferroptosis to promote their own growth by employing defense mechanisms, such as activating System Xc-, boosting glutathione peroxidase 4 (GPX4) activity, and altering glutathione (GSH) metabolism." (PMID 38273826, 2023). "The HepaRG cells also showed a much higher expression of GPx4, correlating with literature data regarding GPx4 functioning as a tumor suppressor." (PMID 37189460, 2023). "To further clarify the role of GPX4 in the anti-tumor effect of IM, we overexpressed GPX4 in GIST-T1 and GIST-882 cells to detect the change of IM sensitivity and its effect on lipid ROS and GSH/GSSG ratio." (PMID 38110356, 2023). "Total tumor tissue protein was then extracted for western blot analysis of GPX4 and HIF-1 expression levels." (PMID 37742011, 2023). "Recently, studies have shown the important role of ferroptosis in reversing tumor drug resistance, as it can inhibit phospholipid glutathione peroxidase 4 (GPX4) and the accumulation of lipid ROS in cells to trigger drug-resistant cancer cell death." (PMID 37092860, 2023). "It has been reported that RSL3 and FIN56 can specifically inhibit GPX4 to induce the ferroptosis of tumor cells." (PMID 37198609, 2023). "Intratumoral depletion of ACSL4 or overexpression of GPX4 reduces tumor necrosis and aggressiveness." (PMID 36937406, 2023). "Combined treatment with brequinar and sulfasalazine can induce ferroptosis, suppressing GPX4′s high tumor growth." (PMID 37373183, 2023). "As previously reported, ferroptosis-inducing nanoreactors (Au/Fe-GA/Sorafenib@PEG) can disrupt the redox homeostasis in tumor cells by suppressing the expression of P-gp and GPX4 after laser irradiation." (PMID 37894410, 2023). "Studies suggest that an iron-rich diet or Gpx4 depletion can induce ferroptosis in tumour cells, releasing 8-hydroxy-2′-deoxyguanosine (8-OHdG)." (PMID 38273826, 2023). "The expression of GPX4 in tumor tissues was positively correlated with the expression of FAAH (Y = 0.8701*X + 0.16, P < 0.0001)." (PMID 37024452, 2023). "Double IF staining finally suggested that mice with FOXA2 absence exerted lower GPX4 and Nrf2 positive expression in tumor areas of AOM/DSS‐treated colons." (PMID 37875418, 2023). "The study also demonstrated that the polymeric carriers depleted NADPH in tumor cells under hypoxic conditions, leading to depletion of GSH and Trx and further inhibition of GPX4 activity, thereby sensitizing tumor cells to ferroptosis." (PMID 37213276, 2023). "Even more exciting, GPX4 expression is obviously reduced during tumor recurrence, whereas acyl-CoA synthetase long chain family member 4 (ACSL4) expression exhibits an obvious increase." (PMID 36937406, 2023). "This, in turn, inhibits cystine uptake by tumor cells, resulting in the depletion of cysteine and glutathione and impaired GPX4 activity, ultimately promoting ferroptosis in tumor cells." (PMID 38136274, 2023). "Studies have shown that compared to normal tissues, the expression level of GPX4 in tumor tissues is significantly increased." (PMID 37658132, 2023). "More importantly, according to our analysis, GPX4 and ACSL4 are significantly associated with various oncogenesis-related signaling pathways, such as the tumor proliferation signature pathway, the EMT, angiogenesis and the tumor inflammation signature pathway." (PMID 37739961, 2023). "MSCPF can inhibit the expression of SLC7A11, GPX4, and P-gp, thereby enhancing the accumulation of sorafenib in tumor cells and improving the antitumor effect." (PMID 37894410, 2023). "In the present study, we found that a novel route enhanced the anti-tumor effect of Sora by affecting the mitochondrial GPX4 PTM." (PMID 37554285, 2023). "Conversely, the tumor tissue exhibited elevated relative expression levels in all isoforms, except for gpx4, which remained unchanged, and gpx5, which exhibited alterations solely in female animals." (PMID 37761814, 2023).
tumor (continued). "Another report showed that cystine promotes GPX4 synthesis through activation of the mTORC1-4EBP signaling axis in a variety of tumor cell lines." (PMID 36966152, 2023). "Several small-molecule drugs have been recognized as inhibitors of GPx4 that were originally pointed out as a modulator of ferroptosis in cancer/tumor cells." (PMID 38202704, 2023). "In 2020, our group achieved the rapid aggregation of lipid peroxides in tumor cell membranes by deactivating GPx4 and enhancing ROS generation in tumor cells." (PMID 37215569, 2023). "IHC images showed that the positive staining patterns for SLC7A11 and GPX4 were observed in the cell membrane of tumour tissues." (PMID 37807410, 2023). "Specific deletion of GPX4 in Tregs results in lipid peroxide accumulation and ferroptosis of Tregs, suppresses tumor growth, and enhances antitumor immunity." (PMID 36861444, 2023). "The genetic suppression of GPX4 was proven to induce ferroptosis in tumor cells and inhibit tumor growth." (PMID 37248295, 2023). "As an anti-tumor effects, a classical ferroptosis inducer is associated with the System Xc-/glutathione (GSH)/glutathione peroxidase 4 (GPX4) axis, which plays a central role in the regulation of the antioxidant system and lipid peroxidation." (PMID 37491375, 2023). "Meanwhile, the depletion of GSH and the inhibition of GPX4 expression sensitized tumor cells to PDT." (PMID 37894410, 2023). "The ferroptosis activator RSL3, an inhibitor of the antioxidant system, directly inactivates GPX4 and inhibits tumour growth in a xenograft mouse model of BJeLR cell origin." (PMID 38273826, 2023). "We determined that DHAA and IKE + DHAA delocalize and deplete GPX4 in tumor cells, specifically inducing lipid droplet peroxidation, which leads to ferroptosis." (PMID 37752118, 2023). "In fact, GPX4-knockout cells were highly sensitive to icFSP1 treatment, and the tumour growth of GPX4-knockout cells was substantially inhibited in the corresponding xenograft tumour model." (PMID 37380771, 2023). "As GPX4 is a crucial endogenous negative regulator of ferroptosis, we analyzed the expression of GPX4 in 40 tumor tissues and 40 paired peritumor tissues of HCC patients from the TCGA-LIHC dataset." (PMID 37554285, 2023). "In a xenograft model, BT inhibited tumor growth without significantly changing the mouse weight, downregulated GPX4, and induced lipid peroxidation, further supporting that BT exerts a tumor-suppressing effect with fewer side effects." (PMID 37488128, 2023). "A diverse cohort of patients with 33 tumor types was grouped into high- and low-expression groups according to the median GPX4 expression." (PMID 38065948, 2023). "The gene of cAMP response element-binding protein (CREB) is highly expressed in tumor tissues and controls the production of GPX4." (PMID 37833746, 2023). "The results showed that GPX4 overexpression significantly reversed the anti-tumor effect of IM and the up-regulation of lipid ROS." (PMID 38110356, 2023). "We first used GPX4 inhibitors to induce tumor immunogenicity and showed that LAR tumors are hypersensitive to GPX4 inhibitors." (PMID 36861444, 2023). "Obviously, XK-81 decreased the protein expression of SLC7A11 and GPX4 in tumor tissues, hinting at the occurrence of ferroptosis." (PMID 37513222, 2023). "Immunohistochemistry (IHC) analyses of tumor tissues confirmed that CRTC3 knockout enhanced the expressions of GPx4 in vivo." (PMID 37666810, 2023). "H&E staining and immunohistochemistry showed that knockdown tumor tissue had decreased ki67, decreased cyclinD1, and decreased GPX4 expression." (PMID 38040698, 2023). "There was a significant difference in GPX4 expression between tumor and normal tissues, and its expression in tumor tissues and paired normal tissues was also significantly different." (PMID 37973560, 2023). "Lastly, specific ablation of GPX4 in Treg cells suppresses tumor growth and boosts anti-tumor immunity." (PMID 37063835, 2023).